OR52E8 (olfactory receptor family 52 subfamily E member 8)
Description:
Odorant receptor.
Synonyms: OR11-54
Tractability: Antibody: UniProt predicts a signal peptide or a membrane-spanning region; its Gene Ontology location is reachable by antibodies, with medium confidence.
Gene: Protein-coding gene on chromosome 11 (5,856,749 to 5,857,690, reverse strand). Ensembl gene ENSG00000183269.
Subcellular location: Membrane
Pathways (Reactome):
Sensory Perception: Expression and translocation of olfactory receptors
Gene Ontology:
Molecular function: olfactory receptor activity; G protein-coupled receptor activity
Biological process: detection of chemical stimulus involved in sensory perception of smell; G protein-coupled receptor signaling pathway; nervous system process
Cellular component: plasma membrane; membrane
Genetic constraint (gnomAD): Loss-of-function variants: 0 observed, 0.0749 expected, observed/expected ratio (o/e) 0, 90% interval 0 to 1.89. That is too few expected variants to judge how well the gene tolerates losing a copy. Missense variants: 451 observed, 392.26 expected, observed/expected ratio (o/e) 1.15, 90% interval 1.06 to 1.24. Synonymous variants: 167 observed, 141.53 expected, observed/expected ratio (o/e) 1.18, 90% interval 1.04 to 1.34.
Homologues: Orthologues: chimpanzee OR52E8 (99% identical), dog OR52E8 (88% identical), mouse Or52e8 (85% identical), rat Or52e8b (85% identical), mouse Or52e8b (84% identical), rat Or52e8 (83% identical), tropical clawed frog or52m1 (45% identical). Paralogues in human: OR52E6 (89% identical), OR52E4 (68% identical), OR52E5 (66% identical), OR52E2 (65% identical), OR52J3 (59% identical), OR52D1 (58% identical), OR52E1 (57% identical), OR52H1 (56% identical), OR52B2 (55% identical), OR52K1 (53% identical), OR52B6 (53% identical), OR52K2 (53% identical), and 39 more.